ZFP36 (ZFP36 zinc finger CCCH-type)
Diseases named in the same sentence as ZFP36 in open-access papers (continued):
Sharing a sentence is not in itself a finding about the gene and the disease.
esophageal cancer (3 papers, 2021 to 2025). A primary or metastatic malignant neoplasm involving the esophagus. "Significantly, the IHC staining and correlation analysis showed that OTUD3 positively correlated with ZFP36 expression levels but was reversely associated with VEGF-C expression levels in the 228 esophageal cancer specimens." (PMID 34853315, 2021). "The PLAs and dual-IF staining revealed that OTUD3 and ZFP36 colocalized in the cytoplasm of esophageal cancer cells." (PMID 34853315, 2021). "Conversely, silencing of OTUD3 decreased ZFP36 in esophageal cancer cells, and this effect was abolished under the treatment of proteasome inhibitor MG132." (PMID 34853315, 2021). "Significantly, ZFP36 strongly reduced VEGF-C mRNA levels in TBL1XR1-overexpressing esophageal cancer cells, resulting in robust inhibition of TBL1XR1-mediated LEC migration and tube formation." (PMID 34853315, 2021). "We overexpressed ZFP36 in nicotine-treated or OTUD3-silencing esophageal cancer cells." (PMID 34853315, 2021). "Finally, we assessed the OTUD3/ZFP36/VEGF-C axis’s clinical relevance in esophageal cancer specimens." (PMID 34853315, 2021). "Indeed, FBXW7 promoted the ubiquitination and degradation of ZFP36 in esophageal cancer cells." (PMID 34853315, 2021). "Downregulation of OTUD3 expression by Nicotine in esophageal cancer leads to downregulation of ZFP36, which induces VEGF-C production and promotes lymphatic metastasis in esophageal cancer." (PMID 37829187, 2023). "Taken together, we here show that nicotine-mediated OTUD3 downregulation facilitates ZFP36 protein degradation and inhibits VEGF-C mRNA decay, leading to robust tumor-induced lymphangiogenesis and lymphatic metastasis in esophageal cancer." (PMID 34853315, 2021). "Downregulation of OTUD3 and ZFP36 is essential for nicotine-induced VEGF-C production and lymphatic metastasis in esophageal cancer." (PMID 34853315, 2021). "In studies on human esophageal cancer, OTUD3 directly interacted with ZFP36 and stabilized the ZFP36 protein by cleaving the K48-type polyUb chain, which subsequently promoted the degradation of vascular endothelial growth factor-C (VEGF-C) mRNA to inhibit lymphatic metastasis." (PMID 41050073, 2025). "OTUD3 and ZFP36 were potently downregulated, while VEGF-C was elevated in the freshly collected esophageal cancer samples from the heavy-smoking patients compared to those from non-smokers, suggesting a significant relevance of the OTUD3/ZFP36/VEGF-C axis in primary tumors." (PMID 34853315, 2021). "Notably, nicotine potently decreased ZFP36 expression in esophageal cancer cell lines and tumors, and these effects were abrogated by OTUD3 overexpression, suggesting that OTUD3 mediated the nicotine-induced ZFP36 downregulation." (PMID 34853315, 2021). "Moreover, silencing of FBXW7 inhibited polyubiquitination of ZFP36, increased ZFP36 protein expression, and reduced VEGF-C expression in OTUD3-silencing esophageal cancer cells, suggesting that downregulation of FBXW7 rescues the effects of OTUD3 depletion in ZFP36 and VEGF-C expression." (PMID 34853315, 2021). "Notably, ZFP36 abrogated the transcriptional or post-transcriptional upregulation of VEGF-C to retain it at a low level, resulting in substantial repression of lymphatic metastasis of esophageal cancer cells." (PMID 34853315, 2021). "This study establishes that the OTUD3/ZFP36/VEGF-C axis plays a vital role in nicotine addiction-induced lymphatic metastasis, suggesting that OTUD3 may serve as a prognostic marker, and induction of the VEGF-C mRNA decay might be a potential therapeutic strategy against human esophageal cancer." (PMID 34853315, 2021).
glioblastoma (3 papers, 2015 to 2023). The most malignant astrocytic tumor (WHO grade IV). "ZFP36 is an mRNA binding protein that exerts anti-tumor activity in glioblastoma by triggering cell death, associated to an increase in the stability of the kinase RIP1." (PMID 25939870, 2015). "A panel of six different glioblastoma-derived GNS cell lines were screened for ZFP36 expression, which resulted to be very heterogeneous (data not shown)." (PMID 25939870, 2015). "LncDLEU1 binds to ZFP36 and facilitates the degradation of ATF3 mRNA by ZFP36, thus upregulating the expression of SLC7A11 to attenuate erastin-induced ferroptosis in glioblastoma." (PMID 37686142, 2023). "To understand the important role of ZFP36 and other key genes in the survival and prognosis of GBM, we analyzed the bulk RNA-seq data of tumor samples and their corresponding survival data by downloading the “Glioblastoma (TCGA, Cell 2013)” data." (PMID 35693633, 2022).
periodontitis (3 papers, 2021 to 2024). An acute or chronic inflammatory process that affects the tissues that surround and support the teeth. "Among these upregulated genes during periodontitis, Egr1, Atf3, and Zfp36 code for transcription factors that regulate expression of genes associated with control of inflammatory responses." (PMID 39588378, 2024). "Comparing the Average global expression profile of neutrophils from healthy PDL versus neutrophils from PDL with periodontitis revealed increased expression of genes such as Il1b, Il1rn, Cebpb, Colec12, Ptgs2, Zfp36, Egr1, Atf3, Csf1, and Lars2 in periodontitis." (PMID 39588378, 2024).
psoriasis (3 papers, 2020 to 2023). An autoimmune condition characterized by red, well-delineated plaques with silvery scales that are usually on the extensor surfaces and scalp. "Moreover, we provide evidence that ZFP36 undergoes methylation in psoriasis, by virtue of the presence of long stretches of CpG dinucleotides both in the promoter and the coding region." (PMID 33585499, 2020). "Eventually, in the absence of mutations or genomic loss events that could explain TTP downregulation during the pathogenesis of psoriasis, we provide evidence supporting the idea that ZFP36 downregulation in psoriasis might depend on epigenetic mechanisms." (PMID 33585499, 2020). "In order to clarify the causes of TTP downregulation during the pathogenesis of psoriasis, and since no relevant mutation or genomic loss event affecting ZFP36 has been described in literature, we hypothesized that this occurrence might depend on epigenetic mechanisms." (PMID 33585499, 2020).
sarcopenia (3 papers, 2011 to 2024). Progressive decline in muscle mass due to aging which results in decreased functional capacity of muscles. "In the sarcopenia dataset, BTG2 (AUC = 0.867), CDKN1A (AUC = 0.892), CEBPB (AUC = 0.942), DDIT4 (AUC = 0.792), FOXO3 (AUC = 0.900), NFKBIA (AUC = 0.892), ZBTB16 (AUC = 0.808) and ZFP36 (AUC = 0.775) demonstrated better diagnostic efficacy in distinguishing sarcopenia patients from healthy controls." (PMID 38962732, 2024). "The results showed a strong positive correlation (p < 0.01) between NFKBIA and effector.Memory.CD4.T.cell and memory.B.cell, while ZFP36 had a strong negative correlation with both eosinophils and type 2.T.helper.cell cells (p < 0.01) in the sarcopenia datasets." (PMID 38962732, 2024).
viral infection (3 papers, 2018 to 2024). "Strikingly, loss of ZFP36 in vivo accelerated T cell responses to acute viral infection and enhanced anti-viral immunity." (PMID 29848443, 2018). "The RNA-binding protein ZFP36 promotes K63-linked polyubiquitination of RIG-I, thereby facilitating RIG-I activation during viral infection." (PMID 39466846, 2024). "In summary, antigen-specific T cell response is clinically functional but accelerated in Zfp36 KO mice during viral infection." (PMID 29848443, 2018). "In vivo studies of acute viral infection showed accelerated expansion and recession of virus-specific CD4 + and CD8+T cells in Zfp36 KO animals." (PMID 29848443, 2018). "Collectively, these in vivo studies demonstrate an accelerated T cell response to viral infection in the absence of ZFP36, which may reflect the heightened activity of multiple cell types in addition to T cells." (PMID 29848443, 2018).
bladder cancer (2 papers, 2021 to 2022). "The frequency of ZFP36 gene family mutations ranged between 9.1 and 10%, among the three bladder carcinoma cohorts; notably, mutations of ZFP36L1 and ZFP36L2 were mutually co-occurring (P = 0.02; FDR = 0.06)." (PMID 33397444, 2021). "When we combined mutations of ZFP36L2 and ZFP36 to ZFP36L1, the frequency of ZFP36 gene family mutations reached 3% (n = 297) in all TCGA cohorts, with the highest frequencies observed in bladder cancers." (PMID 33397444, 2021). "Interestingly, AREG, ATF3, ZFP36, and DUSP1 were all associated with inflammation and cancer, specifically enrichment of adipocytokine signaling, bladder cancer, epithelial cell signaling in Helicobacter pylori infection, and JAK/STAT signaling pathways in patients with high AREG expression." (PMID 35372438, 2022).
diabetic kidney disease (2 papers, 2023 to 2024). Progressive kidney disorder caused by vascular damage to the glomerular capillaries, in patients with diabetes mellitus. "Three necroptosis-related biomarkers, EGF, PAG1, and ZFP36, were identified and showed strong diagnostic ability for diabetic kidney disease." (PMID 37988198, 2023). "Therefore, we focused on the role of necroptosis in diabetic nephropathy (DN) and identified EGF, PAG1, and ZFP36 as potential biomarkers associated with necroptosis using the WGCNA algorithm." (PMID 37988198, 2023).
dilated cardiomyopathy (2 papers, 2024 to 2025). Cardiomyopathy which is characterized by dilation and contractile dysfunction of the left and right ventricles. "An integrated analysis has identified zfp36 as a key target in dilated cardiomyopathy." (PMID 40000392, 2025). "In our study, genes regulated by AP-1, namely CDKN1A, SAT1, and ZFP36, were found to be downregulated in DCM (dilated cardiomyopathy) myocardium compared to normal myocardium." (PMID 38886541, 2024).
epilepsy (2 papers, 2016 to 2017). A brain disorder characterized by episodes of abnormally increased neuronal discharge resulting in transient episodes of sensory or motor neurological dysfunction, or psychic dysfunction. "Several SRF-controlled genes that were identified in the present study (e.g., Cyr61, Bdnf, Zfp36, Fos, JunB) are upregulated in the cortex in patients who suffer from epilepsy." (PMID 25636686, 2016).
gastric cancer (2 papers, 2022 to 2024). A primary or metastatic malignant neoplasm involving the stomach. "We found that MAPKAPK5 and USP1 proteins were highly expressed in gastric cancer tissues, while the ZFP36 protein was lowly expressed in tumor tissues." (PMID 35719376, 2022).
glioma (2 papers, 2015 to 2022). A benign or malignant brain and spinal cord tumor that arises from glial cells (astrocytes, oligodendrocytes, ependymal cells). "To test the relevance of our data, we assessed the ability of ZFP36 to control RIP1 stability in human glioma neural stem cell lines (GNS), as this population shows resistance to standard therapy and is believed to mediate tumor recurrence." (PMID 25939870, 2015). "We previously demonstrated that ZFP36 acts as tumor suppressor in glioma cell lines by inducing necroptotic cell death and we speculated that RIP1 stabilization could be responsible for the execution of this death program." (PMID 25939870, 2015). "Interestingly, it has been shown that ZFP36 sensitizes transformed cell lines to TNF alpha-induced cell death and we have recently described the role of ZFP36 in promoting necroptosis in glioma cell lines." (PMID 25939870, 2015). "Finally we demonstrate that loss of ZFP36 in glioma cancer stem cells leads to the down-regulation of RIP1, thus reinforcing the molecular link between ZFP36 and RIP1." (PMID 25939870, 2015). "Moreover, we show that ZFP36 controls RIP1 levels in glioma neural stem cell lines." (PMID 25939870, 2015).
head and neck squamous cell carcinoma (2 papers, 2024). A squamous cell carcinoma that arises from any of the following anatomic sites: lip and oral cavity, nasal cavity, paranasal sinuses, pharynx, larynx, and salivary glands. "The role of ZFP36 in OSCC has not been fully explored, but it has been linked to head and neck squamous cell carcinoma (HNSCC)." (PMID 38351596, 2024).
Hypertension (2 papers, 2022 to 2025). The presence of chronic increased pressure in the systemic arterial system. "Moreover, the VSMC‐specific depletion of ZFP36 inhibited AngII‐induced hypertension and vascular remodeling in mice, whereas ZFP36 deficiency attenuated hypertension in SHR rats." (PMID 39589932, 2025). "Moreover, the VSMC‐specific ZFP36 deficiency attenuates AngII‐induced hypertension and vascular remodeling in mice." (PMID 39589932, 2025). "Specifically, ZFP36 levels were increased in the arteries of patients and animals with hypertension." (PMID 39589932, 2025). "Given the key role of ZFP36 in blood pressure, ZFP36 inhibitors have potential applications as a therapeutic strategy to treat hypertension and vascular diseases in humans." (PMID 39589932, 2025). "To explore the role of ZFP36 in hypertension, we first re‐analyzed single‐cell sequencing data of the aorta of SHR and Wistar rats from the GSE149777 dataset." (PMID 39589932, 2025). "Immunofluorescence and immunohistochemistry staining results revealed that ZFP36 levels were significantly higher in the mesenteric arteries and aortas of patients with hypertension than in those with normotension." (PMID 39589932, 2025). "To further confirm the role of ZFP36 in the pathogenesis of hypertension, we analyzed its expression in the arteries of patients and rats with hypertension." (PMID 39589932, 2025). "Given the critical role of AngII and homocysteine (Hcy) in hypertension and vascular diseases, whether they regulated ZFP36 expression was determined." (PMID 39589932, 2025). "AAV‐mediated ZFP36 knockdown ameliorates spontaneous hypertension in rats." (PMID 39589932, 2025). "ZFP36 inhibition represents a new therapeutic strategy for treating hypertension." (PMID 39589932, 2025). "Moreover, ZFP36 knockout alleviated AngII‐induced hypertension and vascular remodeling in mice, whereas decreased ZFP36 expression ameliorated hypertension in spontaneously hypertensive rats." (PMID 39589932, 2025). "The injection of AAV9‐shRNA targeting ZFP36 ameliorated hypertension in SHR rats." (PMID 39589932, 2025). "Thus, VSMC ZFP36 plays an important role in the pathogenesis of hypertension." (PMID 39589932, 2025). "ZFP36 inhibition may represent a new therapeutic strategy for the treatment of hypertension." (PMID 39589932, 2025). "Thus, targeting ZFP36 is a potential strategy for the treatment of hypertension." (PMID 39589932, 2025).
inflammatory bowel disease (2 papers, 2021 to 2023). A spectrum of small and large bowel inflammatory diseases of unknown etiology. "In immune cells, differential gene expression analysis revealed that genes associated with immune regulation, biotic stimulus, and inflammatory bowel disease (IBD) were significantly upregulated, including Zfp36, Ptpn22, and Isg2017–19." (PMID 37488127, 2023).
injury (2 papers, 2021 to 2022). Damage inflicted on the body as the direct or indirect result of an external force, with or without disruption of structural continuity. "To confirm our finding that ZFP36 could prevent CREBBP-induced lung injury through mRNA degradation, we measured the effect of altering the expression of ZFP36 on the level of CREBBP mRNA in the intestinal I/R-induced lung injury mouse model." (PMID 34238924, 2021).
iron deficiency (2 papers, 2022 to 2025). "Previous studies have demonstrated that 2 members of the ZFP36 family play a role in cardiac function; deletion of Zfp36l1 and Zfp36 (also known as Ttp) causes embryonic heart defects and cardiomyopathy in iron deficiency, respectively." (PMID 35316214, 2022).
lung fibrosis (2 papers, 2021 to 2022). "ZFP36 deficiency upregulated CREBBP, enhanced I/R-induced lung injury, apoptosis, and inflammation, and increased I/R-induced lung fibrosis." (PMID 34238924, 2021). "Analysis of lung tissues in ZFP36-knockdown mice by Western blotting, immunohistochemistry, and real-time PCR showed that ZFP36 deficiency upregulated CREBBP, enhanced I/R-induced lung injury, apoptosis, and inflammation, and increased I/R-induced lung fibrosis." (PMID 34238924, 2021).
lymphoma (2 papers, 2014 to 2021). A malignant (clonal) proliferation of B- lymphocytes or T- lymphocytes which involves the lymph nodes, bone marrow and/or extranodal sites. "The RNA-binding protein Tristetraprolin (TTP, ZFP36) functions as a tumor suppressor that impairs the development and disables the maintenance of MYC-driven lymphoma." (PMID 25541715, 2014).
myeloma (2 papers, 2022 to 2025). "ZFP36 encodes an RNA-binding protein, TTP, which downregulates two key factors in myeloma growth and proliferation - CyclinD1 and E2F1." (PMID 34983615, 2022).
myocardial infarction (2 papers, 2022 to 2023). Gross necrosis of the myocardium, as a result of interruption of the blood supply to the area, as in coronary thrombosis. "The expression of STAT3 and ZFP36 was different only within 24 h after myocardial infarction." (PMID 36407421, 2022). "Moreover, we showed that ZFP36 regulates human coronary endothelial cell proliferation and defined that VEGF-C administration in vivo enhances clonal expansion of the cardiac vasculature post-myocardial infarction." (PMID 36082978, 2023).
ovarian carcinoma (2 papers, 2018 to 2021). A malignant neoplasm originating from the surface ovarian epithelium.
alcoholic hepatitis (1 paper, 2025). Acute hepatitis resulting from ingestion of alcohol. "Bioinformatic analysis of the expression of TTP family members in patients with alcohol-related cirrhosis or alcohol-related hepatitis reveals a significant decrease in the LSM7 gene, as well as a significant increase in ZFP36 and ZFP36L2 in cirrhosis and Lsm4 in alcoholic hepatitis." (PMID 39941720, 2025).
aneurysm (1 paper, 2026). Bulging or ballooning in an area of an artery secondary to arterial wall weakening. "Real-time quantitative PCR (RT-qPCR) results showed that the expression alteration of Zfp36 between normal aorta and aneurysm is most significant among candidates." (PMID 41551919, 2026). "Immunofluorescence (IF) staining revealed that ZFP36 was primarily expressed in VSMCs within the vasculature and was markedly down-regulated in aneurysm." (PMID 41551919, 2026). "Underexpression of ZFP36 was observed in aortic vascular smooth muscle cells (VSMCs) within aneurysms from patients and angiotensin II (AngII)-induced mice." (PMID 41551919, 2026). "First, we chose GBP2 as the primary downstream target of ZFP36 for in-depth investigation based on its high expression and substantial variation in AngII-treated VSMCs and aneurysm." (PMID 41551919, 2026). "We further confirmed the expression profile of ZFP36 in the angiotensin II (AngII)-induced AAA model, and the results of Western blotting (WB), RT-qPCR, and IF were consistent with former findings, indicating a remarkable decreased expression of ZFP36 in aneurysm." (PMID 41551919, 2026).
bacterial meningitis (1 paper, 2015). Inflammation of the membranes surrounding the brain and spinal cord due to a bacterial infection. "Most interestingly, these factors may positively (e.g., IL33 and IL18rap) and negatively (Tnfaip3, CISH and Zfp36) contribute to regulation of NF-κB, which is a hallmark feature of bacterial meningitis." (PMID 25993608, 2015).